CAT (catalase)
Diseases named in the same sentence as CAT in open-access papers (continued):
Sharing a sentence is not in itself a finding about the gene and the disease.
cancer (continued). "The addition of catalase suppressed cancer cell death and confirmed the important role of hydrogen peroxide in this anticancer mechanism of action involving ascorbate." (PMID 38483584, 2024). "Overall, CAT inhibition has the potential to be a novel strategy to induce ferroptosis of cancer cells through the dual regulation of ROS levels and iron ions." (PMID 38891864, 2024). "Similarlly, our study found that the activities of antioxidant enzymes, specifically SOD and CAT, were reduced, while increased lipid peroxidation in silymarin-treated cancer cells." (PMID 39431222, 2024). "We further identified Catalase as a binding partner and substrate of Parkin, which is an important antioxidant enzyme that regulates intracellular ROS levels during cancer progression." (PMID 38424181, 2024). "The nanogel incorporating GOX and catalase (CAT) was fabricated via polymerization, utilizing PpIX and cancer-cell-specific Arg-Gly-Asp (RGD) as comonomers." (PMID 37102898, 2023). "Upward or downward changes in SOD and CAT expression have been reported depending on the cancer type." (PMID 37960210, 2023). "One indirect approach involves increasing the intracellular oxygen levels in cancer cells by using catalase enzymes to break down hydrogen peroxide into oxygen." (PMID 38069213, 2023). "At the same time, many studies have found that ROS levels in tumor cells are generally higher than in normal cells, and cancer cells increase the expression of endogenous antioxidants (e.g., glutathione or catalase) to adapt to this redox state." (PMID 37631285, 2023). "We suggest these findings be taken into account when considering any future development of catalase as a cancer therapeutic." (PMID 37311396, 2023). "The antioxidant enzyme catalase (CAT) provides protection against oxidative stress and downregulation or inactivity of catalase is observed in many cancers." (PMID 36672328, 2023). "There is ample opportunity for characterizing biological effects such as free-radical scavenging, oxidant load, and catalase activity in normal tissues and cancer at different FLASH dose rates." (PMID 37568644, 2023). "Overexpressing the H2O2 scavenging enzyme catalase in the cancer cells obviated the effects of AVA plus radiation therapy on the xenografted tumor growth implicating ROS as H2O2 in the process." (PMID 36066649, 2023). "C60 nanofilm inhibited oxidative stress generated in cancer cells by treating them with a growth factor cocktail due to the increased synthesis of antioxidant enzymes such as catalase in the cells." (PMID 38067256, 2023). "Catalase has been considered to be a remarkable enzyme system in the research of cancer and potential chemotherapy." (PMID 37507999, 2023). "A variety of ROS-scavengers, in addition to isoflavones, were utilized to treat cancer cells, including 700 μM Thiourea, 100 μg/mL Catalase, and 100 μg/mL Superoxide dismutase." (PMID 37049690, 2023). "In their study, CAT improved cancer hypoxia by producing abundant endogenous oxygen, while CD73siRNA efficiently inhibited the expression of the target gene, synergistically down-regulating the level of CD73 and promoting the T cell-specific immune response." (PMID 37514008, 2023). "In normal(cancer) cells, the enzyme ‘catalase’ suppresses both HOCl and ONOO− pathways and restricts the generation of hydroxyl radicals." (PMID 38203693, 2023). "While therapeutic modulation of hypoxia and oxidative stress cannot be excluded on the basis of our results as viable therapeutic strategies in cancer, our results do contradict a growing body of experimental reports of catalase administration effects." (PMID 37311396, 2023). "Its anti-cancer properties are based on antioxidant activity (lowering the concentration of ROS, catalase, and glutathione peroxidase) and anti-inflammatory activity related to the influence on the transcription factor NFkappaβ and Notch-1." (PMID 37570691, 2023).
cancer (continued). "Catalase expression and activity are increased in certain BC cells, suggesting a potential role in enhancing cancer cell survival and proliferation." (PMID 37513179, 2023). "The cytotoxic and genotoxic effects of P-AscH− on NSCLC were reversed by co-treatment with catalase, highlighting the roles of extracellular hydrogen peroxide in anti-cancer activities of P-AscH−." (PMID 37760080, 2023). "Given the lack of effect observed, we propose that further development of catalase as a cancer therapeutic should take these findings into consideration." (PMID 37311396, 2023). "Compared with control cell lines (BEAS-2B), MRPL44 and CYCS were significantly higher expressed in cancer cell lines (A549 and H1299), while CAT was significantly lower expressed." (PMID 36798829, 2023). "The activity of SOD and catalase and their levels in the sera of the control group, cancer groups, and treated rats were assessed during the progression of the disease." (PMID 37765117, 2023). "The activities of SOD and CAT were much higher in the mammary glands of cancer-bearing animals dosed with AM 60 mg/kg than in AM 30 mg/kg treated rats." (PMID 37373429, 2023). "To investigate this possibility, we used catalase as a tool to examine the contribution of extracellular H2O2 to the anti-cancer properties of P-AscH−." (PMID 37760080, 2023). "Most of cancer cells are characterized by lower levels of endogenous antioxidants such as glutathione peroxidase or catalase." (PMID 36296971, 2022). "Meanwhile, elevated expression levels of CAT have been reported in cancer tissues compared to normal counterparts, whereas other studies showed decreased levels of CAT, indicating that cancer cells are frequently more sensitive to oxidative stress." (PMID 36035213, 2022). "One study analyzed the impact of catalase on cancer cells’ resistance to ascorbic acid-mediated oxidative stress." (PMID 35457200, 2022). "Regulation of CAT expression in cancer is known to be multifactorial, including genetic and epigenetic changes, transcriptional and posttranscriptional regulations as well as posttranslational modifications." (PMID 36112236, 2022). "Secondly, it was reported that catalase prevents SOD2 overexpression-induced promotion of cancer cells in vitro and in vivo." (PMID 36552527, 2022). "We investigated several CAT SNPs described previously in the literature, selected according to their role in other autoimmune and chronic diseases, as well as some forms of cancers in which there is an inhibition of CAT." (PMID 36555526, 2022). "Under X-ray radiation, the highest level of DNA damage in cancer cells was observed after treatment with CAT@Pt(IV)-liposomes." (PMID 35119544, 2022). "Further examinations revealed the gene expressions of SOD and CAT were significantly elevated in cancer cells treated with CNP." (PMID 36506910, 2022). "Previous research on kaempferol in a rat cancer model found that the compound had rejuvenating activities due to the activity of the antioxidant enzymes CAT, SOD, and GPx." (PMID 36015135, 2022). "As ROS induce autophagy through several mechanisms involving Atg4, catalase, and mitochondrial electron transport chain in cancer cells, we investigated if ROS mediate induction of autophagy in EAC cells." (PMID 35936716, 2022). "Previously, incubation of LA was shown to reduce the expression of various antioxidant enzymes (e.g., superoxide dismutase (SOD)-1/2 and catalase) on cancer cells." (PMID 35255889, 2022). "Another study focused on stimulation of sonodynamic cancer therapy by utilizing catalase-triggered oxygen production." (PMID 36505711, 2022). "In comparison with normal cells, it has been reported that catalase expression in cancer tissues is altered." (PMID 35794980, 2022).
cancer (continued). "The most potent cancer suppression effect was observed in the group of H2O2@Liposome plus CAT@Liposome therapy, in which the cancer therapy efficacy was the highest compared to RT alone or RT enhanced by CAT@Liposome owing to the cascade reactions." (PMID 34927373, 2022). "Similar to catalase, superoxide dismutase is often used to eliminate excess reactive oxygen species for cyto-protection and cancer therapy." (PMID 35448311, 2022). "Suppressing Adenosine and IDO, increasing the mitochondrial function and cytokine production using PCG1, as well as catalase expression to counteract TME hypoxic conditions by ACAT1 are examples of TME metabolic alterations contributing to cancer improvement." (PMID 36419058, 2022). "The typical method of “oxidation therapy” is to deliver ROS-generating agents to cancer cells directly, including glucose oxidase (GOx), catalase (CAT), methyl quinone (MQ) and cinnamaldehyde (CA)." (PMID 36304902, 2022). "With such a capacity, catalase is often employed to remove excess reactive oxygen species H2O2 or to provide on-demand O2 for cancer therapy and cyto-protection." (PMID 35448311, 2022). "Antibody-mediated CAT inhibition in vitro has emerged as a promising approach in experimental cancer therapy." (PMID 36307808, 2022). "Low activity of CAT was found in patients with pneumonia, atherosclerosis, diabetes, neurodegenerative diseases, nephritis, and cancer." (PMID 34409535, 2022). "Two hub genes, including CAT and APP, are involved in different cancers; for Instance, CAT, positioned specially in peroxisomes, decomposes H2O2, a spinoff of fatty acid oxidation, to oxygen and water." (PMID 36302939, 2022). "Catalase activity according to their results was also reduced, but our research suggested increased catalase activity with time and concentration of NPs in cancer cell lines." (PMID 35936220, 2022). "The failure of cancer treatment is usually related to the high expression of CAT, so inhibiting the expression of intracellular CAT is considered to be a significant means to promote the efficacy of ROS-based catalytic therapy." (PMID 36105309, 2022). "Particularly low values of catalase were observed in patients with cancer of the lung, gastrointestinal tract, kidney or breast, or with leukemia (Ścibior and Czeczot 2006)." (PMID 34409535, 2022). "Although catalase activity varies greatly among cancer cell lines, cancer cells often have low CAT levels." (PMID 36432484, 2022). "It has been clearly demonstrated that cancer cells with lower levels of glutathione peroxidase and catalase are highly sensitive to arsenite." (PMID 36359850, 2022). "Previous studies have shown that the functional CAT is mainly located in peroxisomes; moreover, it has also been found in the cytoplasm, mitochondria, and on the cytoplasmic membrane of human cancer cells." (PMID 35392238, 2022). "The results showed that both SOD and CAT activity were significantly increased p < 0.01 in both sensitive and resistant cancer cells treated with curcumin at a dose of 2.7 μM compared to control non-treated respective cells." (PMID 36143462, 2022). "Due to rapidly proliferating, cancer cells have high H2O2 levels with a low catalase level in comparison with normal cells." (PMID 33468160, 2021). "Glorieux and collaborators have suggested that, in cancer cells exposed to oxidative stress, phosphorylation of catalase would occur and result in decreased catalase activity." (PMID 34381561, 2021). "It was reported that the catalase modulation of heterogeneous Fenton reaction plays a significant character in achieving selective cancer cell eradication." (PMID 33572246, 2021). "The decrease in the enzymatic activity of CAT under U. barbata extracts had a higher amplitude than the CAL-27 cancer cells." (PMID 34356377, 2021). "For example, Au2Pt nanozymes as POD and CAT mimics with potent photothermal performance were reported for PDT/CDT/PTT synergistic cancer therapeutics." (PMID 34241715, 2021).
cancer (continued). "Catalase showed a preventive role against a high-level of pro-apoptotic oxidative stress in cancer cells." (PMID 34829946, 2021). "A specific suppression effect was produced by the released H2S on the CAT activity of cancer cells, resulting in H2O2 facilitating the Fenton reaction of Fe2+ and consequently promoting ROS induction within the cells." (PMID 33789653, 2021). "Various enzyme mimetic nanomaterials, such POD OXD, SOD and CAT mimetic nanozymes, have been extensively studied for use in cancer therapeutics." (PMID 34356639, 2021). "To further elucidate the effects of this difference in catalase in cancer cells vs. normal cells against IR or IR P-AscH− treatment, we used catalase CRISPR/Cas9 KO plasmid knockouts of MIA PaCa-2 and PANC-1 cells (MIA CAT KO and PANC-1 CAT KO)." (PMID 33923601, 2021). "FoxO3a is regulated by Akt signaling pathway; this signaling pathway is said to suppress catalase expression in cancer cells." (PMID 33504098, 2021). "In the present study, lower CAT and higher GPx activities were observed in the cancer patients compared to the healthy control group." (PMID 34721756, 2021). "These anti-cancer effects can be abolished by adding the main detoxifying enzyme catalase to the medium, underscoring a role for H2O2." (PMID 34717701, 2021). "Although studies by us and others have indicated an inverse correlation between the level of CAT expression or activity and resistance to therapy in different cancer cells, other studies have shown divergent results." (PMID 34943091, 2021). "The effectiveness of cancer cells’ antioxidant machinery is also guaranteed through the activity of the catalase enzyme." (PMID 34829946, 2021). "In normal cells, catalase is present to decompose H2O2 into O2 and water, but many cancer cells also appear to have a catalase deficiency." (PMID 34068081, 2021). "In both cancer groups, decreases in vitamin D and CAT, as well as increases in osteopontin and blood plasma MDA, were observed." (PMID 34721756, 2021). "IL-6 was previously reported to induce the expressions of COX-2 34, 35, MMP-9 36, Oct3/4 37, SOD2 38, 39 and CAT 39 in cancer cells." (PMID 33854627, 2021). "For instance, catalase (CAT) a key antioxidant enzyme defense against oxidative stress which played important role in the development of many cancer types." (PMID 34176789, 2021). "Oxidative stress accumulated in cancer cells can also result from excessive H2S due to the suppression of the enzyme catalase (CAT) which is recognized as the most vital enzyme for the decomposition of H2O2." (PMID 33789653, 2021). "On the other hand, it was shown that catalase contributed to the increased resistance of cancer cells to pro-oxidant drugs (especially in H2O2-mediated processes)." (PMID 33419097, 2021). "The elevated catalase activity confers strong protections against cancer by reversing the malignant phenotype via decreasing the cellular levels of ROS production (mainly H2O2)." (PMID 34394838, 2021). "Several studies indicated that catalase activity significantly decreased in many cancers through SP stimulation and increased ROS production." (PMID 33976938, 2021). "A positive correlation was found between livin/BIRC7 expression and serum catalase activity and malondialdehyde level in endometrial hyperplasia and carcinoma." (PMID 34568983, 2021). "The ability of 808-nm wavelength laser light to interact with cell photo-acceptors localized into the mitochondria respiratory chain and the catalase enzyme negatively impacts carcinoma cell homeostasis." (PMID 34829946, 2021). "An increase in the levels of antioxidants like SOD and catalase, both in the frontal cortex and hippocampus in treatment groups, showed that DHZ is actively reversing the cell damage caused by both cancer and TMZ." (PMID 32995109, 2020).
cancer (continued). "Since CAT plays an important role in metabolism and redox balance of cancer cells 16, H2S is expected to be a potential gaseous inhibitor to fulfill the needs of CAT suppression in specific therapeutic applications." (PMID 32685012, 2020). "In general, overexpression of CAT, an intrinsic characteristic of cancer cells, plays a vital role in initiation and progression of cancer and resistance to various therapies." (PMID 32274323, 2020). "The effective suppression of CAT within cancer cells has therefore been anticipated as a potential methodology to promote the efficacy of hypoxia-triggered therapeutics." (PMID 32685012, 2020). "Although only using catalase to relieve hypoxia can achieve good results, it is far from meeting the needs of clinical cancer." (PMID 33343807, 2020). "[[qv: 9]] A high expression of CAT has been found in various types of tumor cells specifically, which is primarily responsible for the failure of cancer therapy." (PMID 32274323, 2020). "Fe2+ release effectively induces hydroxyl radical via the Fenton reaction, while intracellular H2S gas selectively suppresses catalase activity of cancer cells, enabling promoted reactive oxygen species induction and remarkable antitumor performance." (PMID 32274323, 2020). "Pre-treatment with N-acetyl-l-cysteine and antioxidant enzymes (superoxide dismutase and catalase) significantly suppressed AG-1-induced toxicity, suggesting that superoxide and hydrogen peroxide contribute to AG-1-induced toxicity in human cancer cells." (PMID 31991904, 2020). "It is well known that the production of H2O2 is higher in cancer cells compared to normal cells but cancer cells have a lower ability to eliminate H2O2 due to the low level of expression in catalase and glutathione peroxidase." (PMID 32055716, 2020). "More importantly, the intracellular H2S induced effective inhibition to the CAT activity specifically in the Huh7 cancer cells, and in turn promoted the intracellular content of H2O2 and amplified the production for toxic ROS significantly." (PMID 32274323, 2020). "In the present study, we develop a mathematical model to analyze the proposed catalase-dependent anti-cancer effect of CAP." (PMID 33096638, 2020). "It has been demonstrated that the specific cytotoxicity of ascorbate to cancer cells is H2O2-dependent because the addition of catalase can decrease the cytotoxicity of ascorbate to sensitive cancer cells." (PMID 32560478, 2020). "Currently, there are several approaches to inhibit CAT in cancer therapy, aiming to elevate cellular ROS levels and thus inducing apoptosis in cancer cells." (PMID 32605023, 2020). "They reported that MIA PaCa-2 cells have a low basal capacity to remove H2O2 and a markedly low catalase activity compared with those of several other cancer cell lines, making them the best model for H2O2-generating agents." (PMID 32517328, 2020). "Correspondingly, the hydrogels loaded with calcium peroxide microparticles or glucose oxidase/catalase enzymes enabled the precise and efficient in vivo photocontrol of gel degradation and drug release for cancer treatment." (PMID 33015634, 2020). "Low doses of hydrogen peroxide and superoxide stimulate cell proliferation in a wide variety of cancer cell types which is evident from our study where SOD and catalase activity are highly favouring to cancer cells with low oxidative stress." (PMID 32158360, 2020). "More interestingly, the intracellular H2S induced effective inhibition to the CAT activity specifically in the Huh7 cancer cells, and in turn promoted the intracellular content of H2O2 and amplified the subsequent Fenton reaction for toxic ROS production." (PMID 32274323, 2020). "Studies conducted on 10 types of normal cell lines and 15 cancer lines support the thesis that reduced catalase activity increases the sensitivity of cancer cells, and catalase can be a marker of the effectiveness of vitamin C therapy." (PMID 32455696, 2020).